IL32 (interleukin 32)
Diseases named in the same sentence as IL32 in open-access papers (continued):
Sharing a sentence is not in itself a finding about the gene and the disease.
urothelial carcinoma (1 paper, 2025). A malignant neoplasm derived from the transitional epithelium of the urinary tract (urinary bladder, ureter, urethra, or renal pelvis). "To further investigate the therapeutic potential of CXCL13, CCL19, and IL32 for urothelial carcinoma, we performed Cox survival analyses in eight distinct cohorts." (PMID 39739621, 2025).
ZIKV infection (1 paper, 2020). "IPA also predicted many cytokines, including IL-15, IL-27, IL-32, C5, IL-18, and EB13, were significantly up-regulated by ZIKV infection in HSerC." (PMID 32511241, 2020).
tumor (134 papers, 2004 to 2026). "This study explores the relationship between IL-32 expression and prognosis, the tumor immune microenvironment, genetic mutations, RNA methylation, immunoregulatory effects, and related signaling pathways in different tumors through pan-cancer analysis." (PMID 38584169, 2024). "In our clinical observations, immunohistochemistry results revealed a positive correlation between tumor‐p‐Src or p‐Akt and pericyte‐IL32 levels in our EGFR‐mutated patient cohort." (PMID 39435643, 2024). "This is further supported by conflicting reports in cancer, as increased IL-32 levels associate with enhanced anti-tumor immunity and good patient prognosis in cutaneous melanoma but tumor progression in many epithelial cancers." (PMID 39211051, 2024). "The analysis indicated that six genes (PIK3CA, CDC27, B2M, PTEN, SMAD4, and IL32) were strongly associated with tumor-infiltrating lymphocytes." (PMID 35903675, 2022). "The IL32-immunopositivity has been associated with greater depth of tumor invasion, lymph node involvement, and venous invasion, which we failed to observe in our cohort, either at protein or mRNA level." (PMID 33020452, 2020). "Tumor location in the left side of the colon (n = 14) tended to be associated with greater IL-32 protein concentration than in the right side (n = 20) (by 1.3-fold)." (PMID 33020452, 2020). "In a model of breast cancer, IL-32 secreted by CAFs promotes metastasis in vivo via activation of β-integrin-mediated p38MAPK signaling in tumor cells, inducing loss of cell-cell adhesion and promoting cell migration." (PMID 33114328, 2020). "Tumor location in the left side of the colon (n = 10) was associated with higher IL32 upregulation (by 3.3-fold) than in the right side (n = 11)." (PMID 33020452, 2020). "Several molecules, including IL-10, IL-32, epidermal growth factor and growth arrest-specific gene 6, have been associated to the tumour-promoting function of TAMs." (PMID 31480312, 2019). "Another important group of immune-associated genes regulated by anisomycin included KITLG, IL-6, IL-32, and IL-3RA, which encode cytokines and cytokine receptors to mediate potential survival signals or growth signals in tumour cells." (PMID 30006566, 2018). "Furthermore, we identified a significant increase in interleukins and tumour necrosis factors, including IL‐1a, IL‐1b, IL‐6, IL‐17C, IL‐32, IL‐36G and TNF, along with its associated enzyme." (PMID 39865778, 2025). "In the present study, based on data mining analysis of various databases, we comprehensively analyzed the expression of IL32 and its association with tumor-infiltrating immune cells and related immune markers and further evaluated the prognostic value of IL32 in predicting survival outcomes." (PMID 38584169, 2024). "IL-32 can modulate the activity of tumor-associated macrophages and induce tumor inflammation." (PMID 39235457, 2024). "In our study, we observed increased circulating IL32 associated with the early tumor stage, indicating that IL32 may serve as a biomarker for the early stage of CRC." (PMID 37228491, 2023). "IL32 is highly expressed in various tumours, but with distinct effects depending on the tumour type." (PMID 41457346, 2026). "The upregulation of IL32 has been shown to act as a tumor suppressor in several cancers, including PC." (PMID 40001606, 2025). "The expression levels of IL11, IL23A, IL27, and IL32 were significantly correlated with tumor stage." (PMID 40612864, 2025). "Pro-inflammatory cytokines such as IL-6, IL-8, IL-16, and IL-32 were included due to their involvement in tumor growth, angiogenesis, and chemoresistance." (PMID 40652770, 2025). "CXCL-12 in tumor and IL-32 in ascites were positively correlated with increased surgery duration, indicating their role in systemic inflammation." (PMID 40652770, 2025). "In contrast, in other cancers, IL-32 can promote tumor cell apoptosis and enhance the toxicity of NK cells, thereby exerting an inhibitory effect on tumor growth." (PMID 41181127, 2025).
tumor (continued). "IL11 (p = 0.010), IL23A (p = 1.77e − 05), IL27 (p = 1e − 05) and IL32 (p = 0.001) exhibited significant correlations with tumor stage." (PMID 40612864, 2025). "Here, we used patient-derived tumor fragment (PDTF)-based 3D HYGTIC because of the unavailability of murine anti-IL32 antibodies (method)." (PMID 38343549, 2024). "This provides an initial explanation for the regulatory mechanism of IL32 expression within the tumor microenvironment." (PMID 39435643, 2024). "Further understanding of the regulatory mechanisms of IL-32 and its isoforms in the progression of malignant tumors is of great significance for clinical judgment of tumor prognosis and treatment strategies." (PMID 38584169, 2024). "IL-32 exhibits both pro- and anti-tumor effects, but the majority of the effects promote tumor growth." (PMID 39235457, 2024). "Co‐injection of cancer cells with PCs reduces tumor responsiveness to TKIs, with IL32/β5‐integrin depletion restoring sensitivity." (PMID 39435643, 2024). "This study elucidates the role of IL32 in tumor development from multiple perspectives, providing some strategies for further research into the specific mechanisms of IL32 in cancer progression and treatment." (PMID 38584169, 2024). "Previous reports have suggested that high IL32 expression can promote the proliferation and metastasis of tumor cells, such as in PRAD19, PAAD20, and THCA21." (PMID 38584169, 2024). "T cells are major IL-32 producers in these diseases and key mediators of pathogen and tumor elimination but also autoimmune destruction." (PMID 39211051, 2024). "Tumor immune cell infiltration was assessed using the CIBERSORT computational method as well as the ESTIMATE method to analyze the correlation of IL32 expression with stromal and immune components." (PMID 38584169, 2024). "In tumor cell cultures IL-32 was detected in intracellular vesicles and, thus, neighboring cells can be exposed to IL-32 through the uptake of extracellular vesicles released from IL-32 expressing cells." (PMID 39211051, 2024). "Considering that inflammation is one of the critical factors for the initiation of tumor development and progression, IL-32 production by ENO1 stimulation is closely related to tumorigenesis." (PMID 38675491, 2024). "The correlation of IL32 expression with pathological tumor staging in the TCGA cohort was done, and it was raised as T stages increased in PRAD (p = 1.4e-4), KIRC (p = 2.6e-3), PAAD (p = 1.2e-3)." (PMID 38584169, 2024). "Further analysis of cell‐cell communications via ligand‐receptor interactions unveiled robust communication between the subset of IL32‐positive pericytes and tumor cells expressing β5‐integrin (gene name: ITGB5)." (PMID 39435643, 2024). "IL-32 mRNA levels have been found to increase in tumoral samples, and, when cultured, tumor viability has been impaired by adding anti-IL-32 antibodies, confirming the potential effect of IL-32 on MF and SS viability and progression." (PMID 38607023, 2024). "For example, IL‐32 and TGFβ act as mediators facilitating cross‐talk between breast CAFs and cancer cells, promoting tumour cell proliferation and invasion." (PMID 39690134, 2024). "The findings revealed that C1 CALR+MCs, C2 ALOX5+MCs, C3 ANXA2+MCs, C5 IL32+MCs, myeloid cells, fibroblasts, and SMCs are capable of targeting tumor cells by releasing TWEAK." (PMID 39224598, 2024). "We performed triple immunostaining for α‐SMA, CD34, and IL32 on tumor sections to quantify the percentage of pericyte‐IL32 positive blood vessels in each patient, indicating that IL32 was expressed in PCs." (PMID 39435643, 2024). "Additional mechanisms explained the IL-32 anti-tumor activities through its ability to modulate other cytokines and immune cells including TNF-α." (PMID 36845147, 2023).
tumor (continued). "While the Tumor_2 had relative mild cancer hallmark signatures but expressed genes associated with tumor survival signal and drug resistance (IL32, TOX2, AIF1, AKAP12, CD38 etc.), and eventually became the main tumor subtype post-treatment." (PMID 36417130, 2023). "Depletion of IL-32 from three different MM cell lines reduces proliferation and cell survival as well as tumor growth in vivo." (PMID 37313466, 2023). "Although IL-32 is generally considered pro-inflammatory due to its ability to activate NFκB signalling and p38 MAPKs and enhance tumor immunity, it can exert anti-inflammatory effects under certain circumstances." (PMID 37727785, 2023). "Firstly, we analyzed the expression difference of IL-32 between tumor tissues and the paired peritumor tissues by RNA microarray." (PMID 35428295, 2022). "We also analyzed the GEO cohorts (GSE23400, GSE20347 and GSE45670) and found that IL-32 expression was higher in ESCC tumor tissues than peritumor tissues." (PMID 35428295, 2022). "Although most IL-32+ cells were tumor cells, there were also a proportion of IL-32+CD206+ cells in ESCC tissues." (PMID 35428295, 2022). "Several studies showed that the overexpression of IL-32, specifically α, β, and γ were able to reduce tumor growth through inducing apoptosis in tumor cells, which led to CD8+ T-cell responses." (PMID 35281008, 2022). "We firstly detected the secretion of IL-32 in cultured supernatant of tumor cells (EC109 shNC, EC109 shIL-32, KYSE150 vector, and KYSE150 IL-32β) via ELISA assay." (PMID 35428295, 2022). "Expression level of IL-32 was positively correlated with the pathologic stage (P < 0.05), tumor stage (P < 0.05), as well as lymph node metastasis (P < 0.05, P < 0.01)." (PMID 35428295, 2022). "IL-32 overexpression facilitated lung metastasis and was positively correlated with the proportion of M2 macrophages in tumor microenvironment." (PMID 35428295, 2022). "In the lung metastasis mouse model, we also found that there were more metastatic nodes (Both in size and number) in IL-32 overexpression group, which was positively correlated with the increased M2 macrophages in tumor microenvironment." (PMID 35428295, 2022). "In this review, we address that the paradoxical effect of IL-32 on cancer is attributed to the dominant isoform, cancer type, tumor microenvironment, and genetic background." (PMID 35281008, 2022). "The influence of IL-32 in tumor growth through the inactivation of NF-κB and signal transducer and activator of transcription 3 (STAT3) pathways have been mentioned earlier." (PMID 35281008, 2022). "IL-32 plays a contradictory role such as tumor proliferation or suppressor in cancer development depending on the cancer type." (PMID 35281008, 2022). "In cancer, inflammatory tumor microenvironment such as cytokines, IL-32 plays a crucial role in its progression." (PMID 35281008, 2022). "Consistent with the results of RNA microarray, strong staining of IL-32 was detected in the cytosol of tumor cells." (PMID 35428295, 2022). "We observed that the expression of IL-32 was abnormally higher in ESCC tumor tissues (n = 84, P < 0.001)." (PMID 35428295, 2022). "The results show that IL-32 have an ability to promote M2 macrophage polarization in the primary tumor microenvironment." (PMID 35428295, 2022). "Analysis of the phenotype and proportion of M2 macrophages showed that human tumor cells with high IL-32 expression promoted the polarization of M2 macrophages in the primary tumor microenvironment." (PMID 35428295, 2022). "This systematic analysis provides evidence suggesting the potential role of IL32 as an effective biomarker for patient survival in the tumor microenvironment." (PMID 34682815, 2021). "Data showed that IL-32 expression in T and NK cells in tumor tissues was slightly higher in comparison to the adjacent tissues." (PMID 34414188, 2021).
tumor (continued). "IL-32 was the most significantly upregulated cytokine, which has been shown to play a crucial role in tumour initiation, proliferation and maintenance." (PMID 35582010, 2021). "Date showed that in CD4+ T cells, naive CD4 and Treg cells in tumor expressed much more IL-32 than adjacent tissue, and in CD8+ T cell subsets, IL-32 expression was much higher in adjacent than tumor tissues." (PMID 34414188, 2021). "IL-32 reduced tumor growth and rendered immune checkpoint inhibitor-resistant tumors responsive to anti-PD-1 therapy without toxicity." (PMID 33827575, 2021). "Our data suggest that IL-32 is potentially involved in the regulative function of T and NK cells and plays an important role in tumor surveillance." (PMID 34414188, 2021). "We used published scRNA-seq data to analyze the IL-32 expression in ESCC CD45+ tumor-infiltrating immune cells." (PMID 34414188, 2021). "This confirmed that higher expression of several known CTCL marker genes, including CD27, IL-32, CXCL13, BATF, and TIGIT28–32, was associated with spots with higher frequencies of tumor cells (see yellow highlighted genes)." (PMID 34795254, 2021). "IL-32 induces immune cell recruitment and limits tumor growth via the induction of a chemokine-rich TME." (PMID 32841222, 2020). "Studies with murine transgenic models showed that overexpression of IL-32 (α, β, and γ) inhibited the growth of murine tumors by inducing tumor cell apoptosis, leading to CD8+ T cell responses." (PMID 32841222, 2020). "Collectively, these data show that an increased infiltration and activation of CD8+ T cells is indispensable for IL-32–induced tumor control." (PMID 32841222, 2020). "IL-32–treated tumors displayed an approximately 3-fold increase in absolute numbers of CD8+ T cells within the tumor as well as significantly increased frequencies of IFN-γ+ and Nur77-GFP+ CD8+ T cells." (PMID 32841222, 2020). "Collectively, these findings provide robust evidence for the therapeutic efficacy of IL-32 as a tumor immunotherapy, in particular, for patients whose cancers exhibit immune excluded TME." (PMID 32841222, 2020). "Together, our findings suggest that IL-32 in combination with anti–PD-1 is a viable and save strategy for inducing tumor immunity in a wide range of immune excluded tumor types, which fail to respond to ICB monotherapy." (PMID 32841222, 2020). "Here, we show for the first time to our knowledge that direct administration of IL-32 leads to increased frequencies of tumor-infiltrating T cells in multiple poorly immunogenic mouse tumor models." (PMID 32841222, 2020). "In the B16F10 model, intratumoral administration of IL-32 as well as cGAMP significantly reduced the tumor growth in the treated primary tumors as well as in the untreated contralateral tumors." (PMID 32841222, 2020). "CD8+ T cell depletion abolished the efficacy of IL-32 in both the primary treated tumor and untreated contralateral tumor." (PMID 32841222, 2020). "Thereby, IL-32 treatment reduced tumor growth and rendered ICB-resistant B16F10 tumors responsive to anti–PD-1 therapy without toxicity." (PMID 32841222, 2020). "Using hierarchical clustering analysis followed by application of a threshold to linkage distance, we delineated 5 protein clusters in tumor samples, of which cluster 1 contained co-upregulated chemokines and proinflammatory cytokines in IL-32–treated tumors." (PMID 32841222, 2020). "First, we found that IL-32 is primarily expressed in tumor-infiltrating T cells and acts in a paracrine fashion on myeloid cells." (PMID 32841222, 2020). "Solely in ESCC, fold-change in IL-32 protein concentration (tumor-to-adjacent) was dependent on cancer stage." (PMID 33020452, 2020). "Tumor sublocation in the colon had an impact as well ‒ patients with left-sided tumors (n = 19) had significantly more elevated IL-32 than those with right-sided tumors (n = 22)." (PMID 33020452, 2020).